RET (ret proto-oncogene)
Diseases named in the same sentence as RET in open-access papers (continued):
Sharing a sentence is not in itself a finding about the gene and the disease.
thyroid tumor (continued). "In particular, the RET/PTC3 rearrangement, in which RET is fused to the promoter region of the NCOA4 gene (also known as ELE1), was described in a post-Chernobyl thyroid tumor." (PMID 33572167, 2021). "For instance, in many it was shown that the RET/PTC oncogene, a thyroid tumor, induces genes which are involved in inflammation, such as chemokines and cytokines." (PMID 33324647, 2020). "When rearranged with RET, CCDC6 contributes aminoterminus portions corresponding to 101aa, identified in most of the cases of lung and thyroid tumours, or portions corresponding to 150aa or 293aa, reported at very low percentage in thyroid tumours." (PMID 29455670, 2018). "The results of this study demonstrated that motesanib inhibited thyroid tumor xenograft growth, predominantly through the inhibition of angiogenesis and possibly via the direct inhibition of VEGFR2 and RET, which were expressed in tumor cells." (PMID 23509459, 2013). "The upregulation of Bim mRNA expression decreased over time, and by 8 months of age, Bim expression levels had returned to baseline in RET/PTC3 Dicer1(+/+) and RET/PTC3 Dicer1(+/−) thyroid tumors, reaching values comparable to those observed in the WT condition." (PMID 41002430, 2025). "While Ogg1 mRNA expression was not modified, we observed a downregulation of Gpx2 and Nqo1 mRNA expression in thyroid tumors from 2- and 8-month-old RET/PTC3 Dicer1(+/+) mice compared to WT thyroids, suggesting that redox homeostasis is unbalanced in RET/PTC3 tumors." (PMID 41002430, 2025). "Although thyroid tumors weights from RET/PTC3 Dicer1(+/+) and RET/PTC3 Dicer1(+/−) mice were not significantly different, RET/PTC3 Dicer1(−/−) tumors exhibited slightly slower growth curves and reduced tumor weight at 4 and 8 months of age." (PMID 41002430, 2025). "RET SSVs have been described in thyroid tumors in general but have not been extensively studied in MTC." (PMID 38566816, 2024). "RET/PTC rearrangements analysis on thyroid tumor has not been extensively performed in Korea, given the prevalence of the BRAF V600E mutation in PTC in Korea." (PMID 28417935, 2017). "Second, whether the Shh pathway is involved in thyroid tumor initiation or facilitates tumor development initiated by oncogenes, such as mutant BRAF, RAS, or RET, needs to be verified in a transgenic mouse model." (PMID 29163356, 2017). "The CCDC6 gene was originally identified because of its rearrangement with the RET tyrosine kinase in thyroid tumors, and with genes other than RET in non-solid tumors." (PMID 25885523, 2015). "The prevalence of RET/PTC rearrangements in thyroid tumors of patients who had no history of neck irradiation ranges from 2.5 to 35% among different series." (PMID 23133451, 2012). "Similarly, the RET inhibitor pralsetinib demonstrated a 53% ORR across RET-fusion-positive non-NSCLC/non-thyroid tumors, with particularly promising results in pancreatic cancer (3/3 responders) and cholangiocarcinoma (2/3 responders)." (PMID 41153346, 2025). "Similarly, Bim mRNA expression levels were upregulated in RET/PTC3 Dicer1(−/−) and RET/PTC3 Dicer1(+/−) thyroid tumors, showing no impact of Dicer1 inactivation." (PMID 41002430, 2025). "Indeed, many thyroid tumors exhibit RET/PTC1 rearrangements, even without a history of radiation exposure." (PMID 39047147, 2024).
multiple endocrine neoplasia (75 papers, 2006 to 2026). Multiple endocrine neoplasia (MEN) is a group of rare inherited cancer syndromes characterized by the development of two or more endocrine gland tumors, sometimes with tumor development in other tissues or organs. "MTC is inherited in 25% of cases, due to mutations in RET proto-oncogene observed in the context of multiple endocrine neoplasia (MEN) syndromes or familial medullary thyroid cancer (FMTC)." (PMID 40095491, 2025). "Hereditary medullary thyroid cancer accounts for 25% of cases, forming part of the multiple endocrine neoplasia syndromes (multiple endocrine neoplasia 2) and is associated with RET proto-oncogene mutation, for which gene testing is increasingly available." (PMID 39555152, 2025). "The major clinical entities included Congenital Adrenal Hyperplasia (CAH) due to pathogenic variants in CYP21A2 gene and Multiple Endocrine Neoplasia (MEN) type 2 due to pathogenic variants in the RET proto-oncogene." (PMID 38637882, 2024). "Although most MTC are sporadic, 25% are familial with germline mutations of the RET proto-oncogene resulting in multiple endocrine neoplasia (MEN) type 2A, type 2B, or familial medullary thyroid cancer (FMTC) with a phenotype-genotype correlation." (PMID 34436027, 2021). "The most frequent RET point mutation detected in multiple endocrine neoplasia syndrome (MEN) type 2A occurs on codon 634, while in 95% of MEN 2B and in 75–95% of sporadic cases the most frequent alteration is RET mutation M918T." (PMID 33803747, 2021). "RET mutations are associated with inducing other endocrine tumors in multiple endocrine neoplasia syndrome (MEN2A and MEN2B)." (PMID 34207842, 2021). "In two sisters we observed a RET gene mutation associated with a diagnosis of multiple endocrine neoplasia syndrome (MEN) type 2A." (PMID 31083609, 2019). "The majority of the cases are sporadic (75%), although approximately 25% of MTC is hereditary due to germline mutation of the RET protooncogene, as seen in multiple endocrine neoplasias (MEN) 2A and 2B." (PMID 26491576, 2015). "For example, in multiple endocrine neoplasia syndromes associated with germline RET mutations, medullary thyroid cancer (MTC) coincides with sympathoadrenal tumors, for which the ancestral cells are established neural crest derivatives." (PMID 26395490, 2015). "Using a yeast two-hybrid screen, we identified Enigma as a new Cbl-c interacting protein which abrogates Cbl-c-mediated ubiquitination and downregulation of RET9MEN2A, a RET isoform associated with multiple endocrine neoplasia (MEN) type 2A." (PMID 24466333, 2014). "This examination of the genotype–phenotype correlation in a substantial cohort of individuals carrying a pathogenic variant of the RET proto-oncogene with the potential to initiate the manifestation of multiple endocrine neoplasia syndrome aligns with existing guidelines." (PMID 38339246, 2024). "However, mutations in RET proto-oncogene are also present in 97% of individuals with multiple endocrine neoplasia (MEN) 2A (MEN2A)." (PMID 29983117, 2018). "Hereditary MTC, whether isolated or part of multiple endocrine neoplasia, is caused by activating RET mutations; one-third of sporadic cases has the same pathogenesis." (PMID 26395490, 2015). "In the remaining 20% of cases, MTC arises in individuals with multiple endocrine neoplasia syndrome (MEN, types 2 A and 2B) characterized by the presence of a germline mutation of the RET proto-oncogene with autosomal dominant inheritance." (PMID 40214777, 2025). "These abnormalities are often linked to syndromes such as Multiple Endocrine Neoplasia (MEN-1, MEN-2A, MEN-4) or mutations in genes such as CASR, CDKN1A, CDKN1B, CDKN2C, and RET." (PMID 41597072, 2025). "Although it could carry several types of mutations, like DTC, in almost all familial cases of multiple endocrine neoplasia type 2A (MEN 2A) and 2B (MEN 2B) and about half of sporadic cases mutations in RET gene are detected." (PMID 40061140, 2025).
multiple endocrine neoplasia (continued). "Cases associated with multiple endocrine neoplasia 2A (MEN2A) and multiple endocrine neoplasia 2B (MEN2B) and a case in which a somatic lineage RET mutation have also been reported." (PMID 38647958, 2024). "Germline rearranged in transfection (RET) testing in multiple endocrine neoplasia 2 and 3, and somatic RET testing in sporadic MTC have revolutionized the treatment options available to patients." (PMID 37204852, 2023). "25% of MTCs are of hereditary origin, which is related to the RET proto-oncogene, most occurs as part of multiple endocrine neoplasia (MEN) 2 syndrome, and the remaining occur as sporadic forms." (PMID 33299412, 2020). "Germline mutations in RET, seen in 98% of patients with hereditary MTC, are associated with several clinical conditions including familial MTC (FMTC) multiple endocrine neoplasia (MEN) type 2A, and MEN2B." (PMID 32027681, 2020). "Mutations that constitutively activate RET are always detected in familial forms of MTC and Multiple Endocrine Neoplasia (MEN) 2A and the proliferation of MEN2 patient-derived MTC cell lines is inhibited by Vandetanib." (PMID 30701022, 2018). "For example, mutations at codon 634 of RET are found in approximately 84% of multiple endocrine neoplasia (MEN2A) patients." (PMID 27841748, 2016). "Hereditary medullary thyroid carcinoma (MTC) is a manifestation of multiple endocrine neoplasia (MEN) type 2A and MEN 2B syndromes caused by germline, activating mutations in the RET (REarranged during Transfection) proto-oncogene (10q11.2)." (PMID 25972901, 2015). "Finally, familial MTC, multiple endocrine neoplasia (MEN)-2A or 2B, genetic RET mutation status, and other information about familial MTC cannot be obtained in the SEER database, which prevents us from independently assessing any predictor related to it." (PMID 33299412, 2020). "Moreover, some mutations (VHL, NF1, and RET) are associated to other tumors rather than PGL (for instance, RET is associated to multiple endocrine neoplasia, VHL to hemangioblastomas, etc.), while other mutations are associated with metastatic forms of PGL (SDHB, FH, and SLC25A11)." (PMID 35054115, 2022). "Most MTC cases present point mutations of RET proto-oncogene that can occur sporadically or as hereditary germline events in the multiple endocrine neoplasia syndromes (MEN2A and MEN2B) or in familial medullary thyroid cancer (FMTC)." (PMID 33986723, 2020). "During the analysis of the sample, specific attention was paid during WES to the genes associated with multiple endocrine neoplasia (CDKN1B, RET, MEN1) and TSC genes, but no variants clinically relevant to the described phenotype of the patient were observed." (PMID 34573383, 2021). "Since no other features of multiple endocrine neoplasia (MEN) syndrome were apparent, we characterised the tumor as sporadic and decided against testing for mutations of the RET-protooncogene." (PMID 23958171, 2013).
familial medullary thyroid carcinoma (68 papers, 2006 to 2025). An instance of thyroid medullary carcinoma that is caused by an inherited modification of the individual's genome. "Hereditary medullary thyroid carcinoma (MTC) is caused by germ-line gain of function mutations in the RET proto-oncogene, and a phenotypic variability among carriers of the same mutation has been reported." (PMID 25887804, 2015). "It includes three distinct clinical subtypes, MEN-2a, MEN-2b, and familial medullary thyroid carcinoma (FMTC), associated with a germline missense PV of variable penetrance in the RET proto-oncogene." (PMID 36980956, 2023). "Hereditary medullary thyroid carcinoma (MTC) is characterized by germline RET mutations and in 40–60% of sporadic MTC somatic RET mutations are present, which cause constitutive activation of the RET tyrosinkinase and in consequence MAPK/ERK and PI3K pathway activation." (PMID 28489587, 2017). "Activating point mutations of the TKR RET have been reported in nearly all hereditary cases of MTC; some of these mutations are included in the MEN2A, familial MTC, or MEN2B syndromes in which there is a genotypic/phenotypic correlation between the type of RET mutation and clinical features." (PMID 23509459, 2013).
melanoma (62 papers, 2010 to 2025). A malignant, usually aggressive tumor composed of atypical, neoplastic melanocytes. "We investigated melanoma EV-associated microRNAs (miRs) using the RET transgenic melanoma mouse model and simulated their transfer to normal myeloid cells by transfecting immature mouse myeloid cells and human monocytes." (PMID 38928399, 2024). "Furthermore, a previous report revealed that GDNF stimulation significantly amplified proliferation of human melanoma cells with polymorphism at G691S in c-RET." (PMID 20422010, 2010). "Meanwhile, a correlation between IL-6 levels, phosphorylated STAT3 and CCR5 expression in tumor-infiltrating MDSC was confirmed in a RET transgenic melanoma mouse model." (PMID 38952546, 2024). "These include BRAF in melanoma, RET/PDGFR in renal cell carcinoma, VEGF-A in NSCLC, MEK in melanoma and NSCLC, and PI3K in multiple cancer types." (PMID 38106415, 2023). "In this driverless setting, we revealed rare oncogenic drivers known from melanoma or other cancer types and identified rare actionable tyrosine kinase mutations in NTRK1, RET and VEGFR1." (PMID 36980598, 2023). "In this driverless setting, we revealed rare oncogenic drivers known from melanoma or other cancer types and identified rare actionable tyrosine kinase mutations in NTRK1/3, RET and VEGFR1." (PMID 36980598, 2023). "NGS testing detected key driver alterations at expected prevalence rates: lung EGFR (16%), ALK (3%), RET (1%), melanoma BRAF (43%), colorectal RAS/RAF (67%), among others." (PMID 35323313, 2022). "Intriguingly, germline haploinsufficiency for Ednrb has the opposite effect in the RET mouse melanoma model (Metallothionein-1/RFP-RET; Ednrb+/− mice), in which it accelerates tumorigenesis, with an increase in lung metastases." (PMID 35158973, 2022). "At this dose of 12.6%, 3HBpo retarded RET melanoma growth as much as KD retarded this growth, both in terms of kinetics and complete responses." (PMID 33320838, 2021). "In the RET melanoma model, diet-based host conditioning increased the efficacy of combination ICB (cICB; anti–PD-1 plus anti–CTLA-4), with significant differences observed as early as after the first systemic injection of cICB." (PMID 33320838, 2021). "Since the RET murine melanoma cell line highly expresses mGluR1, this line was utilized for the in vivo experiments." (PMID 34282238, 2021). "Using the RET transgenic mouse melanoma model, which resembles melanoma development in patients, we found a significant reduction of PMN-MDSC in the tumor microenvironment that was associated with a survival benefit upon the therapy with the CXCR2 inhibitor." (PMID 33578808, 2021). "For instance, in a melanoma model that upregulates RET, where it suppresses antitumor T-cell immune responses and promotes melanoma growth." (PMID 33922633, 2021). "We measured the frequency of M- and PMN-MDSC in melanoma lesions (primary skin tumor and metastatic lymph nodes (LN)), the peripheral blood, spleen and bone marrow (BM) by flow cytometry, using the RET transgenic mouse model, which mimics the human situation." (PMID 33578808, 2021). "ATB tended — albeit not significantly — to reduce the protective effect of both nutritional interventions against RET melanoma outgrowth." (PMID 33320838, 2021). "RET melanoma cells were implanted in C56BL/6J mice to induce brain melanoma tumors followed by treatment with BGS or vehicle administered for fourteen days." (PMID 34282238, 2021). "Our examination of active caspase-3 expression revealed that BGS treatment significantly increases caspase-3 expression in RET melanoma cells in vivo (control 42.0 ± 2.89; BGS 52.0 ± 9.6)." (PMID 34282238, 2021). "Our results demonstrated a significantly higher expression of mGluR1 in HT144 and RET melanoma cell lines, and in one patient-derived melanoma cells compared to its expression in the human astrocyte cell line." (PMID 34282238, 2021).
melanoma (continued). "We first examined mGluR1 expression in various human melanoma cell lines and compared them with the RET mouse melanoma cell line used in this study." (PMID 34282238, 2021). "The G691S RET polymorphism was reported to enhance the response of RET to glial cell line-derived neurotrophic factor (GDNF) and was correlated with the aggressive phenotype of pancreatic cancers and cutaneous malignant melanomas." (PMID 32293499, 2020). "Very recently, similar observations have been made in RET transgenic mouse model of melanoma by detecting Ki67− dormant tumor cells in the skin lesions, as well as in the bone marrow associated with the infiltration of Tem phenotypes." (PMID 33115528, 2020). "Since previous studies showed the coincidence of hair graying and melanoma from identical genetic mutations in horses and patients with Werner syndrome, respectively, coincidence of melanoma and hair graying in RET‐mice is possible." (PMID 33159498, 2020). "For example, metronomic doses of paclitaxel have been shown to reduce the frequency of Gr1+ MDSCs in a RET melanoma mouse model." (PMID 33276524, 2020). "RET-transgenic mice of the 304/B6 (RET-Tg) line develop benign melanocytic tumors and MM in a stepwise manner, and they are widely used for the study of melanoma genesis." (PMID 30111721, 2018). "Remarkably, other diagnoses of RET unrelated tumors were found in 23.8% (5/21) of the cases, accounting for a variable tumor origin which was comprised of melanoma, papillary thyroid, parathyroid, gastric, colorectal, breast, and basal cell carcinoma." (PMID 28018431, 2016). "Previously, we established RFP/RET-transgenic mice of line 304/B6 (RET-mice), in which systemic hyperpigmented skin, benign melanocytic tumor(s) and melanoma(s) develop stepwise." (PMID 26033450, 2015). "Real-time PCR analysis of tumors in RET-mice showed that Dtx3l transcript levels in melanomas were about 4-fold higher than those in benign tumors." (PMID 26033450, 2015). "Our previous DNA microarray analysis in a benign melanocytic tumor and a melanoma from a RET-mouse showed increased levels of Dtx3l transcript in melanoma." (PMID 26033450, 2015). "Our in vivo study showed increased expression levels of Dtx3l in melanomas compared to the levels in murine benign melanocytic tumors in RET-mice." (PMID 26033450, 2015). "Immunoblot and immunohistochemical analyses also showed that Dtx3l protein expression levels in melanomas were increased compared with those in benign melanocytic tumors from RET-mice." (PMID 26033450, 2015). "The stepwise evolution of melanoma in RET mice recapitulates the natural history of disease progression in cancer patients, underlining the significance and suitability of this melanoma model to study the effect of CLND on tumor growth and dissemination." (PMID 26575174, 2015). "Previously, we established RFP/RET-transgenic mice, in which systemic hyperpigmented skin, benign melanocytic tumor(s) and melanoma(s) develop stepwise." (PMID 26033450, 2015). "MT/ret+/− transgenic mice (RET mice) expressing the rfp-ret oncogene develop a spontaneous melanoma that constitutively enhances cRET protein expression in the development of melanoma in RET mice." (PMID 24469254, 2014). "Recently, we identified ZFP 28, CD109, and c-RET as melanoma-related molecules through analysis of tumors in RET mice." (PMID 22013435, 2012). "The entire process of melanoma development via tumor-free, benign, premalignant, and malignant stages in RET mice corresponds to the multistep melanomagenesis in humans." (PMID 22013435, 2012). "RFP-RET transgenic mice of line 304/B6 (RET mice) are powerful tools for analyses of melanoma with pre-existing benign lesions." (PMID 22013435, 2012). "We previously reported that constitutively activated RFP-RET-carrying transgenic mice (RET-mice) spontaneously develop malignant melanoma." (PMID 20422010, 2010).